RAD51 (RAD51 recombinase)
Diseases named in the same sentence as RAD51 in open-access papers (continued):
Sharing a sentence is not in itself a finding about the gene and the disease.
cancer (continued). "It has been highly conserved throughout evolution, and until now, no single mutation has been detected in the coding region of RAD51 in any type of cancer." (PMID 26433958, 2015). "Together with the recent reports on RAD51-associated congenital mirror movement disorders, our results point to an important role for RAD51-mediated homologous recombination in neurodevelopment, in addition to DNA repair and cancer susceptibility." (PMID 26681308, 2015). "A number of studies assessed the association between RAD51 135G/C polymorphism and the risk of these cancers in different population." (PMID 24457040, 2014). "Last, the findings highlight the association between Rad51 gene polymorphisms and cancer development and will provide directions for future research on molecular mechanism of cancer." (PMID 24475258, 2014). "Further studies are needed with large sample size and deeper evaluation about the effect of gene-gene and gene-environment interactions on the Rad51 polymorphisms and cancer risk." (PMID 24475258, 2014). "Loss of RAD51 also inhibited associated metastasis not only in syngeneic mice but human xenografts and changed the metastatic gene expression profile of cancer cells, consistent with inhibition of distant metastasis." (PMID 24811120, 2014). "For Rad51 G135C polymorphism, the C allele of G135C polymorphism had significant association with the cancer susceptibility for the homozygote model, allelic genetic model, and recessive genetic model in overall populations." (PMID 24475258, 2014). "Second, we excluded the studies in which genotype frequencies in controls were not in accordance with HWE, providing sufficient evidence for drawing safe conclusions about the association between the Rad51 polymorphisms and cancer risk." (PMID 24475258, 2014). "A large number of molecular epidemiologic studies have been performed on various neoplasms, such as cancer of breast, bladder, lung, head and neck and skin to evaluate the role of RAD51 polymorphisms." (PMID 24930116, 2014). "In the past decade, a number of molecular epidemiological studies have been done to evaluate the association between RAD51 gene polymorphisms (G135C and G172T) and cancer risk in diverse populations, but the results remained controversial." (PMID 24475258, 2014). "The overall odds ratio (OR) with the 95% confidence interval (95% CI) was calculated to assess the strength of the association between Rad51 polymorphisms and cancer risk." (PMID 24475258, 2014). "The associations between Rad51 gene polymorphisms (G135C and G172T) and risk of cancer have been investigated, but the results were inconclusive." (PMID 24475258, 2014). "We performed a systematic meta-analysis to evaluate the association between RAD51 135G/C polymorphism and the risk of these four types of cancer." (PMID 24457040, 2014). "Targeting cancer cells with a construct encoding DTA gene driven by Rad51 promoter had previously shown promise in cultured cancer cells and animal models." (PMID 24742710, 2014). "In this meta-analysis, 54 case-control studies (42 for G135C polymorphism, 12 for G172T polymorphism) were performed to provide the most comprehensive assessment of the relationship between RAD51 polymorphisms and cancer risk." (PMID 24475258, 2014). "Further studies are needed to evaluate the possible gene-gene and gene-environment interactions in the association between Rad51 gene polymorphism and susceptibility to cancer." (PMID 24475258, 2014). "They found SNPs (PARP1 rs8679 T>C and RAD51 rs7180135 A>G) associated with increased bladder and breast cancer risk and with improved cancer specific survival following radiation therapy in bladder cancer." (PMID 24616890, 2014).
cancer (continued). "To date, a number of molecular epidemiological studies have been done to evaluate the association between RAD51 135G>C polymorphism and different types of cancer risk in diverse populations." (PMID 24040396, 2013). "The subsequent proteasome-mediated protein degradation leads to a continuous deficiency of RAD51, which contributes to growth retardation and cell death of cancer cells." (PMID 23341130, 2013). "A number of epidemiological studies have evaluated the association between RAD51 135G>C polymorphism and cancer risk, but the results remained inconclusive." (PMID 24040396, 2013). "A single nucleotide polymorphism in the 5′-untranslated region (5′-UTR) of RAD51 (a G to C substitution at position 135, the G/C polymorphism) can influence cancer risk among BRCA1/BRCA2 mutation carriers." (PMID 24040396, 2013). "A total of 128 articles regarding RAD51 135 G>C polymorphism with respect to cancer were identified." (PMID 24040396, 2013). "First, a systematic review of the association of RAD51 135G>C polymorphism with cancer risk is statistically more powerful than any single study." (PMID 24040396, 2013). "In view of the low frequency of RAD51 paralog mutations, international collaboration of family cancer clinics will be required to more accurately estimate their penetrance and establish clinical guidelines." (PMID 24139550, 2013). "A meta-analysis based on 39 case-control studies was performed to investigate the association between cancer susceptibility and RAD51 135G>C." (PMID 24040396, 2013). "Although we have put considerable efforts and resources into testing possible association between RAD51 135G>C polymorphism and cancer risk, there are still some limitations inherited from the published studies." (PMID 24040396, 2013). "We further examined the association of the RAD51 135G>C polymorphism and cancer risk according to cancer type and ethnicity because there was significant heterogeneity between studies." (PMID 24040396, 2013). "To date, previous published data on the association between RAD51 135G>C polymorphism and cancer risk remained controversial." (PMID 24040396, 2013). "RAD51 is located at chromosome position 15q15.1, a region that exhibits loss of heterozygosity in a large range of cancers, including those of the lung, the colorectum, and the breast." (PMID 24040396, 2013). "In view of the low frequency of RAD51 paralog mutations, international collaboration of family cancer clinics will be required to more accurately estimate their penetrance and establish clinical guidelines in carrier individuals." (PMID 24139550, 2013). "All these findings associate increased level of RAD51 with genomic instability and cancer development." (PMID 23675572, 2013). "The RAD51 gene is located at chromosome position 15q15.1, a region shown to exhibit loss of heterozygosity in a large range of cancers, including those of the lung, the colorectum and the breast." (PMID 16762046, 2006). "Loss of RAD51 function would therefore be expected to result in an elevated mutation rate, leading to accumulation of DNA damage and, hence, to increased cancer risk." (PMID 16762046, 2006). "Thus, it appears that an apparent low level of RAD51 mutations in cancer cells is compensated by an increase in paralogues mutations." (PMID 42133623, 2026). "GT genotype / T allele patients responded well to RT, indicating that RAD51 might predict cancer risk and RT effectiveness." (PMID 41569203, 2026). "In addition, single-gene pan-cancer studies have also inspired us, such as the discovery of the broad diagnostic and prognostic value of RAD51, TRPM7, and CENPA in pan-cancer." (PMID 40108724, 2025). "In addition, it would be important to assess if HELLS-deficient cancer types are hypersensitized by a combination of PARPi and DNA alkylation or RAD51 inhibitors." (PMID 41297801, 2025).
cancer (continued). "Additionally, RAD51 chromatin accumulation was decreased in sodium oxamate-treated cancer cells, accompanied by the upregulation of γH2AX expression; however, lactate increased the association of RAD51 with chromatin and inhibited γH2AX expression." (PMID 40634292, 2025). "Moreover, in cancer cell lines, RAD51 is associated with the regulation of the autophagy pathway and works together with E-box proteins such as USF1, USF2, and MITF to regulate the expression of autophagy-related genes." (PMID 40746357, 2025). "Notably, Rad51 has been shown to be a functional biomarker for HR deficiency in cancer condition known to confer a therapeutic vulnerability in cancer." (PMID 39107280, 2024). "Furthermore, RAD51 is found to be overexpressed in several types of cancer, and implicated in resistance to chemotherapy, in contrast to the other components of the HDR pathway." (PMID 38499540, 2024). "The RAD51 K70I mutation identified in cancer cells might hence cause a deficiency in DNA repair, through defective nucleosome binding, and thus promote cancer progression." (PMID 38509361, 2024). "Notably, RAD51 overexpression can cause abnormal expression of genes associated with cancer development." (PMID 39161621, 2024). "In fact, RAD51 mutations in the RecA fold domain, which contains the catalytic centre for ATP hydrolysis and homologous pairing, have been found in various types of cancer cells." (PMID 38509361, 2024). "If an acute sensitivity is found, one might expect a cytotoxicity associated with TLS polymerase inhibitors in RAD51 paralog-deficient cancer cells." (PMID 36749784, 2023). "Similarly, SKP2, a substrate recognition subunit of the SCFSKP2 ubiquitin ligase complex, boosts DNA damage repair in cancer cells by regulating the expression of Rad51, a critical protein associated with the repair of DSBs." (PMID 38137461, 2023). "Notably, mono-allelic mutations in the RAD51 paralogs have been linked to various cancers and Fanconi anemia-like disorder." (PMID 37843130, 2023). "RAD51AP1, as a DNA‐binding protein that stimulates RAD51 activity, could protect tumor cells against DNA damage and may be linked to cancer development and progression." (PMID 37461802, 2023). "Conversely, several studies have shown that RAD51 downregulation in HR-proficient cancer cells can lead to an HR-deficient phenotype and improve the effectiveness of current therapies, providing the rationale for current efforts to pharmacologically modulate RAD51 activity." (PMID 37550562, 2023). "Rad51 overexpression has been reported to cause the accumulation of DNA damage in precancerous cells; drive chromosome amplification, deletion and translocation; and lead to cancer development and metastasis." (PMID 35332852, 2022). "This study demonstrated that RAD51 might potentially associate with the drug sensitivities of multiple anti-cancer drugs." (PMID 35359409, 2022). "However, we observed that RAD51 overexpression in normal as well as cancer cells was associated with increased DNA breaks and genomic instability but reduced cGAS expression." (PMID 36428789, 2022). "The correlation analysis of RAD51 and immune cell infiltration levels revealed that RAD51 might be closely associated with cancer immune microenvironments in some cancer types." (PMID 35359409, 2022). "One of the deeply explored fields of this study is the association of RAD51 and cancer immunity." (PMID 35359409, 2022). "Here, this study additionally reported the survival association of RAD51 in 8 cancer types, enlarging the cancer type range that RAD51 might be applied in prognosis." (PMID 35359409, 2022). "RAD51 was closely associated with cancer immune microenvironments in some cancer types." (PMID 35359409, 2022). "Therefore, this study aimed to investigate the clinical value of RAD51 for 33 cancer types, regarding the potential of RAD51 as diagnostic, prognostic, and immune therapy predictive biomarkers." (PMID 35359409, 2022).
cancer (continued). "RAD51 was negatively associated with stroma scores in 22 cancer types." (PMID 35359409, 2022). "Results of correlation analysis of RAD51 and immunomodulators revealed that RAD51 might be associated with multiple immunomodulators in different cancer types." (PMID 35359409, 2022). "The first section of this study was to explore whether RAD51 genetic alterations were associated with cancers." (PMID 35359409, 2022). "Interestingly, RAD51 is expressed at high levels in a large proportion of cancers, and elevated RAD51 expression is associated with a bad outcome and reduced response to treatment." (PMID 34208195, 2021). "Furthermore, replication stress-induced RAD51 recruitment remains intact in BRCA2-deficient cancer cells and BRCA2-hypomorphic mutant embryonic stem cells." (PMID 32938550, 2021). "In addition, it was found that BRCA1-deficient SUM149 cancer stem cells are resistant to PARPi, and this resistance is mediated by high levels of RAD51." (PMID 34208492, 2021). "Deletion of Rad51 paralogs in yeast sensitizes cells to DNA-damaging agents, deletion of vertebrate paralogs results in embryonic lethality, and mutations in the human paralogs are associated with multiple types of cancer." (PMID 34573372, 2021). "Increased levels of Rad51 may compensate for deficiencies in other DNA repair pathways in cancer cells and are often associated with poor patient survival prognosis." (PMID 34157114, 2021). "Thus, in several cancers, the inhibition of autophagy promotes DNA damage and a susceptibility to cancer treatment by the downregulation of RAD51." (PMID 34067336, 2021). "Next, we determined whether the expression level of RAD51 was indeed associated with clinical features of various cancer patients." (PMID 34067336, 2021). "Thus, RAD51 is a crucial DNA repair actor in a large majority of cancers, notwithstanding their BRCA proficiency or deficiency." (PMID 34208195, 2021). "Some RAD51 mutations have been detected in different types of sporadic cancer, but whether they cause tumourigenesis remains unclear." (PMID 34316706, 2021). "POLQ expression in different cancer types strongly correlated with the expression of factors involved in response to replicative stress (RAD51, FANCD2, and BLM), instead of genes encoding for several core MMEJ proteins, factors involved in DNA end resection or in canonical NHEJ." (PMID 34201502, 2021). "Pre-clinical models also suggest RAD51 mutations may be associated with resistance to anti-cancer therapeutics that target the HRR pathway." (PMID 34711195, 2021). "Also, the reduced BRCA1 and RAD51 expressions in VHL-mutated cancers highlight the involvement of HIFs in HRR factors down-regulation and radiation-induced DSBs persistence." (PMID 34539584, 2021). "However, the results for the association of RAD51 genetic polymorphisms with cancer development have been contradictory." (PMID 32316696, 2020). "In secondary end point analysis, we next addressed whether HRDetect+ve cancers had an underlying functional defect in HR DNA repair, using RAD51 focus formation in the end of treatment (EOT) biopsy." (PMID 32471999, 2020). "In this context, it will be paramount to use isogenic replacement systems to test fork progression, remodeling and stability with specific RAD51 paralog mutants linked with cancer and Fanconi anemia, to reveal the specific function(s) of these proteins in preventing human disease." (PMID 32669601, 2020). "While cells that overexpress RAD51 are resistant to DNA-damaging agents, including radiation and cisplatin, RAD51 overexpression also causes aberrant and excessive recombination, which promotes genome instability and is observed in many cancer types." (PMID 33015624, 2020).
cancer (continued). "Either way, the rs5030789 in Rad51 seems to be a plausible cancer risk-reducing SNP." (PMID 31905201, 2020). "The recent discoveries that mutations in classical RAD51 paralog genes predispose to cancer and Fanconi anemia encouraged new mechanistic studies on these HR accessory factors, particularly focused on the human proteins and their possible role in the replication stress response." (PMID 32669601, 2020). "A frustrating aspect of studying RAD51 and its regulators in cancer is that variants identified in patients remain VUS; therefore, it is unclear whether or how they contribute to cancer predisposition." (PMID 33015624, 2020). "In addition, RAD51 hyperactivity is thought to contribute fundamentally to the genesis of genome instability and cancer, and RAD51 overexpression leading to hyper-recombination is implicated in malignant transformation." (PMID 31375703, 2019). "Misregulation of RAD51 is associated with genetic instability and cancer." (PMID 31665741, 2019). "This kind of analysis will be particularly useful for investigation of the numerous RAD51 paralog variants of unknown significance found in patient cancer cells which may in the long-term help optimize personalized cancer therapies." (PMID 31584931, 2019). "However, more high-quality papers with a large sample size should be addressed to assess the correlation between RAD51 polymorphisms and cancer susceptibility." (PMID 31886162, 2019). "In addition, some other meta-analyses were conducted to study the correlation between RAD51 polymorphisms and cancers including HNC." (PMID 31886162, 2019). "Indeed, activation of mutated KRAS cancer cells is highly dependent on RAD51 for survival, KRAS mutation-dependent AKT1 stimulates HR and NHEJ activities for DNA DSB repair, and nuclear translocation of EGFR is associated with DNA-PKs for DSB repair." (PMID 31554189, 2019). "Moreover, the AG heterozygote of -4601A/G polymorphism of RAD51 gene was more frequently observed in the first grade of the cancer disease (acc." (PMID 30728902, 2019). "With shortcomings for small-molecule chemotherapeutics in treating RAD51-associated cancer, we hypothesized that an entirely different class of drugs might be successful." (PMID 31375703, 2019). "Polymorphism of the RAD51 also seems to play a role in other types of cancer." (PMID 31186630, 2019). "Overexpression of RAD51, a recombinase involved in DNA repair by homologous recombination (HR), is associated with a more aggressive cancer phenotype and treatment resistance in a variety of tumors, including ovarian, prostate, colorectal cancer, and malignant gliomas." (PMID 29681946, 2018). "A detailed definition of RAD51 mutations linked to functions, emerging from the work we review here, is needed to guide personalized anti-cancer therapies and guide diagnosis based on variants of currently unknown significance." (PMID 30271574, 2018). "Altered RAD51 is linked to cancer and other diseases affected by impaired genome stability." (PMID 30271574, 2018). "However, hundreds of epidemiology studies have tried to correlate specific RAD51 paralog mutations with cancer predisposition using population studies." (PMID 30551670, 2018). "There are other reports of RAD51 SNPs that associate with cancer." (PMID 31435521, 2018). "However, there is a dearth of data reporting the cellular effects of cancer-associated RAD51 variants." (PMID 27513445, 2016). "Indeed, RAD51 has been demonstrated to be an alternative synthetic lethal target in BRCA1-mutated cancers." (PMID 27507046, 2016). "Variant 172 T allele of RAD51 increased cancer risk (OR = 2.81 (1.72–4.58), p < .0001)." (PMID 25743260, 2015).